ECT2 (epithelial cell transforming 2)
Diseases named in the same sentence as ECT2 in open-access papers (continued):
Sharing a sentence is not in itself a finding about the gene and the disease.
breast carcinoma (continued). "Targeting ECT2 phosphopeptides could provide a promising mechanism for controlling poor prognosis seen in DLC1low ER+ breast cancer." (PMID 30278072, 2018). "Furthermore, our phosphoproteomic analysis, for the first time, demonstrated an inverse correlation with high DLC1 expression and lower phosphorylation of ECT2 in breast cancer." (PMID 30278072, 2018). "Importantly, the ECT2 T359-containing phosphopeptide was detected in both basal and luminal patient-derived breast cancers." (PMID 30278072, 2018). "ECT2 has been reported to be overexpressed in a variety of human tumors including breast cancer." (PMID 30278072, 2018). "In addition, the ECT2 T359-containing phosphopeptide was detected in both basal and luminal patient-derived breast cancers breast cancer phosphoproteomics data on the Clinical Proteomic Tumor Analysis Consortium (CPTAC) Assay portal." (PMID 30278072, 2018). "ECT2 has recently been reported to be involved with mechanisms for activating RhoB after genotoxic stress, thereby facilitating cell death after treatment with DNA damaging agents in Breast Cancer." (PMID 22952662, 2012). "DTL, ECT2, MTDH, PRC1 and RFC4 have all been previously implicated in breast cancer; SCUBE2 and STK32B deletions have been found to be related to mental deficits in humans; and ZNF533 has been found to be associated with the Hedgehog signaling pathway in Zebrafish." (PMID 20584321, 2010). "Additionally, ECT2 protein level was highest in Basal-like subtype breast cancers." (PMID 36572949, 2022). "Besides, ECT2 would be a novel target for drug development for breast cancer." (PMID 36572949, 2022). "Furthermore, ECT2 would be a novel target for drug development for breast cancer." (PMID 36572949, 2022). "However, there are rare studies investigating the role of ECT2 in breast cancer." (PMID 36572949, 2022). "In order to gain further support of the role of ECT2 in breast cancer progression and to extend our observations to a clinicopathologically relevant setting, we analyzed the expression of ECT2 and its correlation with clinical behaviors of breast cancer patients." (PMID 32929379, 2020). "To determine whether our findings in T-47D model are cell-line specific or occur in other ER+ breast cancer cell lines, we evaluated ECT2 phosphorylation and protein levels in other ER+ breast cancer cell lines with various endogenous levels of DLC1 expression." (PMID 30278072, 2018). "KCNK1 expression was positively correlated with that of LDHA, Pan Kla, ZWINT, ECT2, ANLN, and EZR, reconfirming that KCNK1 played an important role in the proliferation and metastasis of breast cancer." (PMID 38905316, 2024). "ChIP-qPCR also showed that overexpression of LDHA blocked the inhibitory effect of KCNK1 knockdown on H3K18la and p300 binding of ZWINT, ECT2, ANLN, EZR, and LDHA in breast cancer cells." (PMID 38905316, 2024). "The Oncomine database revealed high levels of ECT2 in HCC, prostate cancer, breast cancer, colon cancer, head and neck cancer, lung cancer, and stomach cancer." (PMID 33558466, 2021). "Here, we found that ECT2 coordinates with USP7 to form a feedforward circuit and promote breast cancer cell survival in a GEF activity-independent manner." (PMID 32929379, 2020). "In the present study, we identify two convergent AS regulatory pathways (ZRANB2 and SYF2 splicing factors converging on ECT2 splicing) that control resistance to Doxo in breast cancer, specifically in ER+ERBB2- tumors (the main subtype of breast cancer)." (PMID 31943118, 2020). "We found that, when staining was scored according to the mean intensity extent of immunopositivity, ECT2 and USP7 together with MDM2 were highly expressed in breast carcinoma samples, and the levels of their expression correlated with each other." (PMID 32929379, 2020). "Next, we found that both ECT2 and USP7 are significantly overexpressed in a subset of breast cancer patients and the levels of these two factors positively correlate with each other." (PMID 32929379, 2020).
breast carcinoma (continued). "To extend our observations to a clinicopathologically-relevant context, we then analyzed the protein expression levels of ECT2, USP7, and MDM2 with breast carcinoma samples and histologically normal mammary tissues." (PMID 32929379, 2020). "IHC results indicated that ECT2 protein was increased in breast cancer tissues compared with non-cancer tissues." (PMID 36572949, 2022). "In this study, by combining samples from tissue microarrays and gene expression data from public databases, we retrospectively evaluated the expression of ECT2 in breast cancer and non-cancer tissues." (PMID 36572949, 2022). "Furthermore, they showed that RACGAP1 improved mitochondrial fission via targeting ECT2 during anaphase and activating the ERK-DRP1 pathway, which promoted the metastatic progression of breast cancer." (PMID 36192752, 2022). "We found ECT2 expression was markedly elevated in metastatic breast cancer tissues relative to non-metastatic tissues." (PMID 36572949, 2022). "Altogether, these data indicate that high inclusion levels of ECT2-Ex5 are a predictive marker of bad prognosis in breast cancer, specifically in the HR+ERBB2- subtype (as opposed to triple-negative tumors) and in patients that were treated with chemotherapy." (PMID 31943118, 2020). "Mechanistically, ECT2 together with USP7, forms a positive feedback loop to control the expression of each other, and the reciprocal stabilization of the two molecules fuels oncogenic MDM2 in breast cancer." (PMID 32929379, 2020). "For example, in breast cancer, PIK3R2 (phosphoinositide-3-kinase, regulatory subunit 2 beta) and ECT2 (epithelial cell transforming sequence 2 oncogene) have a TARGETgene rank of 37 and 272, and with a 3.31 and 4.94 fold change in gene expression of breast cancer tissues, respectively." (PMID 22952662, 2012). "However, it appears that dysregulation of ECT2 is commonly involved in the development of breast cancer without histological or molecular subtype preference." (PMID 32929379, 2020). "Targeting ECT2, USP7 or their interaction molecular interface may, thus, abrogate the positive feedback circuit forming by these two molecules, and provide an effective treatment of breast cancer patients." (PMID 32929379, 2020). "Kaplan-Meier survival analysis from GEO datasets indicates that elevated ECT2 expression predicts poor overall survival (OS), relapse free survival (RFS), distant metastasis free survival (DMFS), and post progression survival (PPS) in patients suffered from breast cancer." (PMID 32929379, 2020). "Since the expression of ECT2 in different subgroups with distinct histological or molecular traits is all elevated, we hypothesized that ECT2 might play a conserved role in survival promotion of all subtypes of breast carcinoma even though its GEF activity is absent or insufficient." (PMID 32929379, 2020). "Here, we uncovered a GEF activity-independent role of nuclear ECT2 in facilitating anchorage-independent growth and survival of breast cancer cells, indicating that the GEF activity is not a prerequisite for ECT2-promoted tumorigenesis." (PMID 32929379, 2020).
lung carcinoma (16 papers, 2011 to 2024). "Subsequently, ROC analysis was performed to assess the diagnostic value of NEK2, DLGAP5 and ECT2 as biomarkers detecting lung cancer." (PMID 28808310, 2017). "Interestingly, a splice variant of ECT2 was recently found to be regulated by paclitaxel in lung cancer cells, and to mediate inhibition of cell proliferation." (PMID 31943118, 2020). "Furthermore, in order to assess the prognostic value of NEK2, DLGAP5 and ECT2 as biomarkers for lung cancer, we investigated the association between the expression levels of each of these targets with survival through Kaplan-Meier analysis." (PMID 28808310, 2017). "Functionally, PKCι-ECT2 signaling drives two signaling pathways required for the transformed growth of lung cancer cells, RAC-MEK-ERK proliferative signaling, and rDNA transcription and expression of ribosomal RNA processing genes." (PMID 35159064, 2022). "To further determine the clinical significance of ECT2 splicing in patients, we tested the relative levels of two ECT2 isoforms in paired lung cancer samples and the adjacent normal tissues surgically obtained from six patients." (PMID 29706628, 2018). "The increased expression of NEK2, DLGAP5 and ECT2 in lung cancer was identified in three GEO datasets." (PMID 28808310, 2017). "The expression levels of NEK2, DLGAP5 and ECT2 were significantly higher in lung cancer patients than in normal subjects." (PMID 28808310, 2017). "In lung cancer and esophagus cancer, cDNA microarrays revealed that ECT2 was frequently overexpressed in the tumors." (PMID 28362321, 2017). "The Cox proportional hazards regression model was also used to evaluate the predictive value of NEK2, DLGAP5 and ECT2 mRNA levels in lung cancer patients." (PMID 28808310, 2017). "Aberrant expression of Rac exchange factors (Rac-GEFs) Ect2 and Vav1/2/3 has been reported in lung cancer, suggestive of a crucial role for the Rac signaling pathway in the progression of the disease." (PMID 22384062, 2012). "Collectively, ECT2 splicing switch participated in paclitaxel-induced lung cancer inhibition." (PMID 29706628, 2018). "Collectively, our results suggest that NEK2, DLGAP5 and ECT2 could be suitable biomarkers for lung cancer diagnosis." (PMID 28808310, 2017). "In this study, we identified and validated the expression of NEK2, DLGAP5 and ECT2 in multiple lung cancer datasets, and the results showed that the expression levels of these three genes were significantly higher in lung cancer patients than in normal subjects." (PMID 28808310, 2017). "Taken together, these findings indicate that NEK2, DLGAP5 and ECT2 overexpression might be used as promising biomarkers for the diagnosis and prognosis of lung cancer." (PMID 28808310, 2017). "Taken together, our findings revealed that NEK2, DLGAP5 and ECT2 might be used as promising biomarkers for the early detection of lung cancer, as well as predicting the prognosis of lung cancer patients." (PMID 28808310, 2017). "ROC analyses showed that NEK2, DLGAP5 and ECT2 levels could also robustly distinguish lung cancer patients from normal subjects, demonstrating high AUC, specificity and sensitivity values." (PMID 28808310, 2017). "Similarly, ROC analyses showed that DLGAP5 and ECT2 levels could also robustly distinguish lung cancer patients from normal subjects, demonstrating high AUC, specificity and sensitivity values." (PMID 28808310, 2017). "The expression levels of NEK2, DLGAP5 and ECT2 were similar to those in our training cohort, with significant differences in expression between tumor and normal, suggesting that the differential expression statuses of these three genes is a common feature of lung cancer." (PMID 28808310, 2017).
lung carcinoma (continued). "The observed up-regulation of the proto-oncogene ect2 that plays a critical role in cytokinesis and repression of the tumor suppressor Lats2, which negatively regulates the cell cycle by controlling G1/S and/or G2/M transition, are important additional changes induced by c-Myc in lung cancer." (PMID 26427040, 2015). "The same tumor, hepatocellular carcinoma, was promoted for recurrence also by the action of ECT2 and, along with NEK2 and DLGAP5, ECT2 was identified via a genome-scale analysis to act as a prognostic biomarker in lung cancer." (PMID 37106813, 2023). "Furthermore, we performed receiver operating characteristics (ROC) analysis to assess the diagnostic value of these lung cancer biomarkers, and the results suggested that NEK2, DLGAP5 and ECT2 expression levels could robustly distinguish lung cancer patients from normal subjects." (PMID 28808310, 2017).
hepatocellular carcinoma (12 papers, 2019 to 2024). A malignant tumor that arises from hepatocytes. "ECT2 overexpression also promoted the polarization of tumor-associated macrophages in hepatocellular carcinoma." (PMID 34367280, 2021). "Furthermore, ECT2 overexpression was reported to stimulate the polarization of tumor-associated macrophages in hepatocellular carcinoma, a cell that suppress the functions of NK and T cells in the tumor microenvironment." (PMID 37106813, 2023). "The ECT2/Rho pathway promotes the growth and metastasis of hepatocellular cancer and is upregulated in the advanced form of the disease." (PMID 39272711, 2024). "ECT2 facilitates early recurrence and metastasis of hepatocellular carcinoma through activation of the Rho/ERK signaling axis and interaction with RACGAP1." (PMID 39100078, 2024). "Xu27 reported that the overexpression of epithelial cell transforming sequence 2 (ECT2) would promote the polarization of M2 macrophages in hepatocellular carcinoma." (PMID 37752167, 2023). "Increased expression of ECT2 has been found in many malignant tumors, such as breast cancer, cholangiocarcinoma, and hepatocellular carcinoma." (PMID 34367280, 2021). "In hepatocellular carcinoma, ECT2 enhances the expression and stability of RACGAP1 and accelerates activation of the ECT2-mediated Rho/ERK signaling axis to promote tumor metastasis." (PMID 31334127, 2019). "In addition to that, ECT2 had the ability to promote M2 macrophage polarization in hepatocellular carcinoma, which in turn suppressed the functions of NK and T cells, which are vital immune cells for fighting against tumor progression." (PMID 37106813, 2023). "Moreover, in hepatocellular carcinoma, it is indicated that RACGAP1 can activate RhoA to function, and it was verified that RACGAP1 enhances the stability of ECT2 to improve ECT2-mediated RhoA activation." (PMID 39858398, 2024).
gastric cancer (11 papers, 2010 to 2026). A primary or metastatic malignant neoplasm involving the stomach. "ECT2 was also associated with the transcriptional program of cancer stem cells in gastric cancer and its elevated expression was correlated with colorectal cancer progression and growth." (PMID 37106813, 2023). "On the other hand, the overexpression of some hub genes such as centrosomal protein 55 (cep55), centrosome-associated protein E (cenpe), and epithelial cell transforming 2 (ect2) indicated a positive effect on the survival of gastric cancer cases." (PMID 35650297, 2022). "Higher expression of ECT2 was associated with worse prognosis in stomach cancer, where its transcriptomic profile was associated with stem cell properties in cancer cells and was suggested as a potential biomarker for cancer cells with stem cell properties." (PMID 36362041, 2022). "The ACRG cohort and Oncomine also showed that high ECT2 expression was associated with poorer prognosis in gastric cancer patients." (PMID 33062405, 2020). "Moving to gastric cancer, an analysis of 52 cancerous specimens attributed ECT2 to the progression of gastric cancer; another study investigated the ECT2 expression gene in tissues and serum of gastric cancer patients and reported it as a new diagnostic marker." (PMID 37106813, 2023). "This study excavated the alternative splicing events in gastric cancer, and found ECT2 might be a biomarkers for diagnosis and prognosis." (PMID 33062405, 2020). "Moreover the overexpression of two other paired genes, i.e. (cep55, cenpe) and (cep55, ect2), revealed a good impact on survival, so that using their agonist may have a synergistic effect on gastric cancer survival." (PMID 35650297, 2022). "The abnormal expression and prognosis prediction of epithelial cell transforming sequence 2 (ECT2) in gastric cancer (GC) has been reported." (PMID 34367280, 2021). "Therefore, ECT2 plays an important role in the occurrence and development of gastric cancer, and may be the basis for GC diagnosis and targeted therapy (Wang, Yan & Liu, 2016)." (PMID 33062405, 2020). "The oncogene ECT2 is overexpressed in several cancer types including PDAC, and correlates with poor outcome in glioma and gastric cancer." (PMID 26993610, 2016).
glioma (11 papers, 2015 to 2024). A benign or malignant brain and spinal cord tumor that arises from glial cells (astrocytes, oligodendrocytes, ependymal cells). "Overexpression of ECT2 is associated with glioblastoma and promotes proliferation and invasion of glioma cells." (PMID 39390804, 2024). "Elevated ECT2 levels have been reported in various human tumors, including lung, pancreatic, liver cancers, and glioma." (PMID 39552710, 2024). "In light of these findings, we illustrated a graphical abstract showcasing the regulatory role of GINS2 in TMZ chemosensitivity through the EGR1/ECT2 axis in glioma cells." (PMID 38467631, 2024). "ECT2 promoted glioma cell proliferation by regulating the expression of the deubiquitinating enzyme PSMD14 to affect the degradation of the TF E2F1." (PMID 38467631, 2024). "ECT2-associated functional rescue experiments in this study also demonstrated that ECT2 promotes the proliferation, clone formation, cell stemness, migration, and invasion of glioma cells." (PMID 38467631, 2024). "The expression of ECT2, was also verified by RT–qPCR in 11 clinical and 23 glioma samples, wherein it was significantly upregulated compared with normal tissues (P < 0.05)." (PMID 38467631, 2024). "In their study, the ECT2 expression levels were increased in glioma cell lines and tissues compared to normal brain tissue and human astrocytes (NHAs) and correlated with the tumor grade." (PMID 35409080, 2022). "Analysis of survival data in gliomas in the Rembrandt (REpository for Molecular BRAin Neoplasia DaTa) dataset showed that patients with increased levels of ECT2 mRNA have a lower survival than those with intermediate levels." (PMID 32555332, 2020). "Overall, these data confirm that the effect of miR-1300 expression is mediated via reduced ECT2 levels, which drive failed cytokinesis and apoptosis in glioma cells." (PMID 32555332, 2020). "To determine whether GINS2’s regulation of the malignant phenotype and TMZ sensitivity of glioma was mediated by ECT2, we overexpressed ECT2 in GINS2 KO cells for rescue experiments." (PMID 38467631, 2024). "Keeping in mind that PTTG1 can mediate glioma cell proliferation, the signaling cascade ECT2/PMSD14/E2F1/PPT11G could be potentially targeted as a therapeutic approach." (PMID 35409080, 2022). "The ECT2/PSMD14/PTTG1 axis promoted glioma proliferation by stabilizing E2F1." (PMID 33381564, 2020). "The Rho family GEFs, VAV3 and Trio, regulate the invasive phenotype of glioma cells, and a recent study identified the two GEFs, Ect2 and Trio, as activators of various Rho GTPases including cdc42 and Rac1 downstream of Tweak and as regulators of cell migration." (PMID 25682201, 2015). "In addition, the mRNA expressions of GINS2 and ECT2 were positively correlated in glioma." (PMID 38467631, 2024). "The CCK-8 and colony formation assays showed that upregulating ECT2 reversed the GINS2 KO-mediated decrease in the proliferative capacity and colony formation ability of glioma cells." (PMID 38467631, 2024). "In this study, we performed ex vivo experiments to discover that GINS2 regulated the malignant phenotype and TMZ sensitivity of glioma cells, likely by promoting DDR through the early growth response protein 1 (EGR1)/ECT2 axis." (PMID 38467631, 2024). "In conclusion, GINS2 regulated the TMZ sensitivity of glioma through the EGR1/ECT2 axis as well as the DDR pathway, and the GINS2–EGR1–ECT2 pathway has clinical implications for predicting the prognosis of glioma patients." (PMID 38467631, 2024). "Therefore, the upregulation of ECT2 reversed the GINS2 KO-mediated reduction in proliferation, stemness, migration, invasion, and TMZ resistance of glioma cells." (PMID 38467631, 2024).